THY1 (Thy-1 cell surface antigen)
Description:
May play a role in cell-cell or cell-ligand interactions during synaptogenesis and other events in the brain.
Synonyms: CD90; CDw90
Tractability: Antibody: its Gene Ontology location is reachable by antibodies, with high confidence; UniProt places it where antibodies can reach, with medium confidence; UniProt predicts a signal peptide or a membrane-spanning region; the Human Protein Atlas places it where antibodies can reach. PROTAC: its protein half-life has been measured.
Gene: Protein-coding gene on chromosome 11 (119,415,476 to 119,424,985, reverse strand). Ensembl gene ENSG00000154096.
Subcellular location: Cell membrane
Subcellular location (Human Protein Atlas): Nucleoplasm; Plasma membrane
Pathways (Reactome):
Metabolism of proteins: Post-translational modification: synthesis of GPI-anchored proteins
Gene Ontology:
Molecular function: integrin binding; protein binding; GPI anchor binding; GTPase activator activity
Biological process: heterotypic cell-cell adhesion; integrin-mediated signaling pathway; positive regulation of cellular extravasation; positive regulation of focal adhesion assembly; regulation of cell-matrix adhesion; angiogenesis; cell-cell adhesion; cell-cell signaling; cytoskeleton organization; focal adhesion assembly; negative regulation of axonogenesis; negative regulation of cell migration; negative regulation of neuron projection regeneration; negative regulation of protein kinase activity; negative regulation of T cell receptor signaling pathway; positive regulation of GTPase activity; positive regulation of release of sequestered calcium ion into cytosol; positive regulation of T cell activation; receptor clustering; retinal cone cell development; T cell receptor signaling pathway; cell adhesion; cell surface receptor signaling pathway; positive regulation of cell adhesion; regulation of cell migration; and 1 more
Cellular component: apical plasma membrane; cell surface; endoplasmic reticulum; extracellular exosome; focal adhesion; axolemma; dendrite; dendrite membrane; external side of plasma membrane; extracellular region; growth cone; membrane raft; neuronal cell body membrane; plasma membrane; glutamatergic synapse; postsynapse; presynapse
Genetic constraint (gnomAD): Loss-of-function variants: 10 observed, 15.69 expected, observed/expected ratio (o/e) 0.64, 90% interval 0.39 to 1.08. The upper end of that interval is the gene's LOEUF score, 1.08, which puts it in group 4 of 6, group 1 being the genes least tolerant of losing a copy. Missense variants: 159 observed, 211.65 expected, observed/expected ratio (o/e) 0.75, 90% interval 0.66 to 0.86. Synonymous variants: 80 observed, 95.06 expected, observed/expected ratio (o/e) 0.84, 90% interval 0.7 to 1.01.
Homologues: Orthologues: chimpanzee THY1 (100% identical), macaque THY1 (93% identical), rabbit THY1 (83% identical), dog THY1 (83% identical), guinea pig THY1 (82% identical), rat Thy1 (71% identical), mouse Thy1 (70% identical), tropical clawed frog thy1 (35% identical), zebrafish thy1 (25% identical), zebrafish si:dkeyp-69c1.7 (20% identical).
Diseases named in the same sentence as THY1 in open-access papers:
THY1 is named in the same sentence as 325 diseases in open-access papers, as found by Europe PMC text mining. Sharing a sentence is not in itself a finding about the gene and the disease. The quoted sentences say what the papers report.
hepatocellular carcinoma (74 papers, 2012 to 2025). A malignant tumor that arises from hepatocytes. "Hepatocellular carcinoma tumors were reported to express a high level of THY1, and such high expression of THY1 is associated with poor prognosis." (PMID 37046850, 2023). "The epithelial cell adhesion molecule (EpCAM) and Thy-1 cell surface antigen (CD90) have been implicated as cancer stem cell (CSC) markers in hepatocellular carcinoma (HCC)." (PMID 35454789, 2022). "Other notable promoters were those of Hoxd10, a tumor suppressor gene whose promoter hypermethylation has been linked to hepatocellular carcinoma, and Thy1 whose expression stimulates liver regeneration." (PMID 35235716, 2022). "HBx-transfected hepatoma cells incubated with CM from HUVECs also expressed mesenchymal genes including Thy1, CDH2, TGFβR1, VIM, and CD133." (PMID 31069171, 2019). "Although the CD90 (Thy-1) was proposed as biomarker of several tumors and cancer stem cells, the involvement of this molecule in the progression of hepatocellular carcinoma (HCC) and other less frequent hepatic neoplasms is still undefined." (PMID 24116172, 2013).
breast cancer (67 papers, 2010 to 2025). A primary or metastatic malignant neoplasm involving the breast. "High expression of THY1 was more likely to cause metastasis of breast cancer, while low expression of CD1B and DOCK2 was likely to cause metastasis of breast cancer." (PMID 32867782, 2020). "In addition, a high expression of Thy1 was associated with poorer recurrence-free survival in breast cancer patients." (PMID 36120336, 2022). "Based on the GenCLiP 2.0 database, only THY1 was associated with breast cancer." (PMID 32867782, 2020). "Additionally, high expression of THY1 was more likely to cause metastasis of breast cancer." (PMID 32867782, 2020). "THY1 was significantly up-regulated in many human cancer (e.g., breast cancer, colorectal cancer, liver cancer, gastric cancer, lung cancer), and the down-regulated THY1 was occurred in brain and CNS cancer, kidney cancer, and ovarian cancer." (PMID 38819947, 2024). "These in vitro results, together with those using cells with silenced β3 integrin in a metastatic model, highlight the importance of Thy-1–integrin interaction in cancer-endothelial cell interactions in melanoma and breast cancer progression and metastasis." (PMID 35733855, 2022). "Here, we describe how the interaction between Thy-1 (CD90) on activated ECs and β3 Integrin on melanoma and breast cancer cells promotes their migration, TEM, and invasion, via a signaling mechanism that involves Ca2+/hemichannel/ATP/P2X7R activation." (PMID 33511115, 2020). "CD1B (CD1b molecule), THY1 and DOCK2 (dedicator of cytokinesis 2) were found to be implicated in the metastatic recurrence of breast cancer." (PMID 32867782, 2020). "Among the key genes, ASPN, DOCK2, THY1 and KYNU were found to be associated with breast cancer based on NCBI Entrez database." (PMID 32867782, 2020). "Altogether, these findings indicate that ATP released through hemichannels leads to the activation of the P2X7R, and that these signaling events are essential for breast cancer cell migration and invasion induced by Thy-1." (PMID 33511115, 2020). "One of the modules identified in male breast cancer was regulated by THY1, a gene involved in invasion and related to epithelial-mesenchymal transition." (PMID 24194916, 2013). "Recently, a small subset of Thy1+/CD24+ cells purified from MMTV-Wnt-1 mammary carcinomas has been found to behave like CSCs." (PMID 20730114, 2010). "Interestingly, a study in a breast cancer model showed that THY-1 is upregulated in cancer stem cells (CSCs) and mediates physical interactions with tumor macrophages." (PMID 37388918, 2023). "Thy1 is a good candidate biomarker for basal-like breast cancer." (PMID 36120336, 2022). "Breast cancer and melanoma cells treated with Thy-1 trigger signals by engaging β3 integrin." (PMID 35733855, 2022). "This was confirmed here for Thy1 and Il7 in 4T1 breast cancer TDLNs." (PMID 35362044, 2022). "Next, we tested whether P2X7R activation was necessary for Thy-1-induced breast cancer cell migration and invasion." (PMID 33511115, 2020). "Here, we tested whether Thy-1 promotes cell migration and invasion of metastatic breast cancer cells through its interaction with β3 Integrin." (PMID 33511115, 2020). "Thus, we assessed cell invasiveness in a Matrigel assay and found that treatment with Thy-1-Fc enhanced invasion of breast cancer cells, compared to TRAIL-R2-Fc-treated or NS controls." (PMID 33511115, 2020). "THY1 and NEU2 may be potential therapeutic targets for breast cancer with brain metastases, and THY1, CD1B and DOCK2 may serve as potential prognostic markers for improvement of brain metastases survival." (PMID 32867782, 2020). "Taken together, we speculated that THY1 may play a role in brain metastases of breast cancer via positive regulation of GTPase activity." (PMID 32867782, 2020).
breast cancer (continued). "In breast cancer cells, Thy-1 interaction in cis is likely to play a regulatory role, maintaining integrins inactive; whereas in trans, Thy-1 triggers a signaling cascade downstream of the integrin in the cancer cell, indicating that it leads to integrin activation." (PMID 33511115, 2020). "THY1 has been used as a marker for hematopoietic progenitor cells, mesenchymal stem cells, and mammary cancer stem cells." (PMID 23423481, 2013). "Thy1, a marker of myoepithelial and fibroblastic cells, has been linked to mammary CSCs, as a small subset of Thy1+/CD24+ cells, comprising 1%–4% of the tumor cells purified from mammary carcinomas in MMTV-Wnt-1 mice, has been found to behave like CSCs." (PMID 20730114, 2010). "However, considering that Thy-1 is reportedly present in MDA-MB-231 breast cancer cells, the Thy-1-integrin interaction in cis could also occur in these cells." (PMID 33511115, 2020). "Therefore, Thy-1 not only promotes migration, but also invasion of breast cancer cells." (PMID 33511115, 2020). "Furthermore, men with THY1 positive breast cancers had significantly inferior survival." (PMID 24194916, 2013). "In cell clusters associated with MSCs or the progeny (i.e., cancer-associated fibroblasts, CAFs) in the whole tumor data, it was evident that MSC-related cells were the major source of THY1 (CD90), CXCL12 and ACTA2 expression in breast cancer patient samples." (PMID 36940196, 2023). "Our results indicate that TNF stimulation increases Thy-1 protein levels, which promotes trans-endothelial migration (TEM) of breast cancer and melanoma cells in a β3 Integrin-dependent manner." (PMID 33511115, 2020). "In the MMTV-Wnt1 model for breast cancer TICs can be isolated based on the cell surface markers CD24+ and CD90+ (Thy1) and the exclusion of CD45 positive leukocytes." (PMID 27542270, 2016). "As CD24+Thy1+ mammary tumor cells from MMTV-Wnt1 mice have been reported to possess TIC properties, we first performed limiting dilution experiments to ask whether CD24+Thy1+ primary tumor cells from MTB;TetO-Wnt1;TTC;rYFP mice were enriched for TICs." (PMID 34088357, 2021). "Besides MYC itself, we find upregulation of other breast cancer stem cell factors (SOX2, SOX18, THY1, EYA1, GLI2, SALL1, GLIS1, CXCR4), suggesting that MYC HME cells adopt a stem-like state." (PMID 31942031, 2020). "Here, we show that Thy-1 induces migration and invasion of metastatic MDA-MB-231 and B16F10 cancer cells, and when upregulated in an activated EA.hy926 EC monolayer, promotes TEM of these breast cancer and melanoma cells in a β3 Integrin-dependent manner." (PMID 33511115, 2020). "We show here in MDA-MB-231 human breast cancer cells and B16F10 mouse melanoma cells that Thy-1 induces migration and invasion of metastatic cancer cells in a β3 Integrin-dependent manner, by increasing intracellular Ca2+, hemichannel opening, ATP release, and P2X7R activation." (PMID 33511115, 2020). "When comparing the mammary carcinomas to the age-matched untreated control mammary gland, the RMECs from mammary carcinomas showed increased expression of Integrin β1, Integrin α6, FAK, and pFAK, as well as decreased expression of Integrin β3, SMA, and Thy-1." (PMID 22022542, 2011). "Furthermore, four other candidate genes SPARC, THY1, IL1B and CXCL8 are reported in this study as the key regulatory genes which can modulate co-regulatory between different clusters in the PPI network of the brain metastasis tumours from breast cancers." (PMID 35045088, 2022). "Thus, we investigated whether this signaling pathway is activated in MDA-MB-231 breast cancer cells and in B16F10 melanoma cells when stimulated with Thy-1." (PMID 33511115, 2020).
liver cancer (67 papers, 2011 to 2025). An epithelial or non-epithelial malignant neoplasm that arises from the liver. "This cis interaction has been particularly analyzed for αvβ3 integrin in ovary and liver cancer cells, where in both cases cis Thy-1/CD90-αvβ3 integrin interaction modulates cancer progression." (PMID 31428610, 2019). "In both articles, Thy-1/CD90 acts as a β3 integrin ligand, however, in liver cancer cells, Thy-1/CD90 is presented as a carcinogenesis promoter, whereas in ovarian cancer, it is an inhibitor of cancer formation." (PMID 31428610, 2019). "To ask whether the properties of tumor in transplant experiment is the same as the original cell line, we used qPCR to analyse the differentiation-related genes including Afp, Albumin and K19, as well as liver cancer stem cell-related genes such as Prom1, Thy-1, Nanog, and Anpep." (PMID 38956432, 2024). "CD90, also known as Thy-1 (thymocyte differentiation antigen-1), is found to be expressed in various cell types such as hematopoietic stem/progenitor cells, hepatic stem cells in human fetal liver, liver cancer stem cells, neurons, fibroblasts, vascular pericytes, and MSC." (PMID 27579043, 2016). "Additional genes related to hepatic cancer stem cells were more expressed in MHN than in SHN, although their fold-changes were lower than 10 (CD133, THY-1, CD44)." (PMID 23185381, 2012).
glioma (45 papers, 2013 to 2025). A benign or malignant brain and spinal cord tumor that arises from glial cells (astrocytes, oligodendrocytes, ependymal cells). "TCF7, THY1, and TGFβ2 are all associated with glioma stemness, leading to immunosuppression." (PMID 35599254, 2022). "THY1 (CD90) expression is associated with glioma cell proliferation and invasiveness." (PMID 35599254, 2022). "These adhesion molecules are known to potentiate cancer stem cell function, supporting the role of the THY1-ITGAX/ITGB2 axis in glioma cell adhesion, survival, and differentiation." (PMID 38515213, 2024). "Interestingly, we also observed an increased abundance of TAM-SPP1 in recurrent glioma patients and their interaction with tumor cells via THY1-ITGAX/ITGB2 signaling." (PMID 38515213, 2024). "In addition, DKK3 interacts with immune system-related proteins, including TCF7, THY1, and TGFβ2, and induces proliferation, angiogenesis, invasiveness, and immunosuppression of glioma cells." (PMID 35599254, 2022). "In addition, THY1 (CD90) expression is a marker of cancer stem cells in high-grade gliomas." (PMID 35599254, 2022). "The methylation of THY1 could be used as prognostic indicator and treatment target for glioma." (PMID 33996602, 2021). "Additionally, the top Kyoto Encyclopedia of Genes and Genomes (KEGG) pathways associated with COL1A1, ITGB1, THY1, and PDGFRA genes included pathways such as “ECM receptor interaction, leukocyte transendothelial migration, platelet activation, focal adhesion, and glioma” among others." (PMID 40817072, 2025). "Our analysis identifies critical ligand-receptor pairs between TAMs and glioma cells that promote tumor progression, such as MIF-CD74/CXCR4, THY1-ITGAX/ITGB2, and ANGPTL2-TLR4." (PMID 38515213, 2024). "Meanwhile, ligand-receptor interactions between THY1 (CD90) and ITGAX/ITGB2 (CD11C/CD18) were observed from glioma cells (Clusters C1, C2, and C4) to TAMs (Cluster C0)." (PMID 38515213, 2024). "The methylation of THY1 decreased in the high-GASC group, which could be a prognostic indicator and treatment target for glioma." (PMID 33996602, 2021). "We also found that the CNVs of DR3 and CIITA were higher in the high-GASC group, and the methylation level of THY1 was lower in the high-GASC group, which could be a potential treatment target for glioma, particularly in HGG." (PMID 33996602, 2021). "Media was collected from glioma-bearing or nontumor-bearing ex vivo brain slices that were either stimulated (Thy1::ChR2+, termed “active conditioned media” or “ACM”) or nonstimulated, spontaneously active (Thy1::ChR2-, termed “conditioned media” or “CM”)." (PMID 41497590, 2025).
lung fibrosis (38 papers, 2010 to 2026). "Consistently, an elevated expression of Thy-1 has been reported in several mouse models of fibrosis, such as Mdr2 deficiency-induced liver fibrosis, bleomycin-induced lung fibrosis, and unilateral urinary obstruction-induced kidney fibrosis." (PMID 36768219, 2023). "Consistently, Thy-1-deficient mice have developed a more severe lung fibrosis upon intratracheal bleomycin administration than wild-type controls, while the overexpression of Thy-1 attenuated fibrosis in a model of acute interstitial pneumonia." (PMID 36768219, 2023). "In direct contrast to the skin findings, Thy-1 deficiency has previously been shown to worsen lung fibrosis induced by intratracheal bleomycin." (PMID 36066980, 2022). "In accord, Thy1-deficient mice develop severe lung fibrosis with increased accumulation of myofibroblasts in comparison to the wild-type mice." (PMID 36358290, 2022). "As our skin findings were divergent from those reported in lung fibrosis, we confirmed that Thy-1–KO mice had increased lung fibrosis, suggesting that loss of Thy-1 truly has organ-specific effects that are profibrotic in lung and antifibrotic in skin." (PMID 36066980, 2022). "The studies of bleomycin-induced lung fibrosis implicated Thy1 in inhibition of TGFβ1-dependent fibroproliferative responses in tissue fibroblasts." (PMID 36358290, 2022). "Of particular relevance to idiopathic pulmonary fibrosis (IPF) is the observation that Thy-1 promoter methylation is associated with a myofibroblast phenotype where loss of Thy-1 occurs alongside increased alpha smooth muscle actin (α-SMA) expression." (PMID 22938014, 2012). "In a murine lung model of bleomycin-induced fibrosis, Thy-1 deficient mice develop more severe lung fibrosis in comparison to wildtype littermates." (PMID 20657842, 2010). "In line, similar effects were observed in bleomycin‐induced lung fibrosis in Thy1‐deficient mice." (PMID 40936326, 2026). "Since lung fibrosis studies have shown that Thy-1 deficiency prevents resolution of fibrosis by regulating myofibroblast apoptosis, this raises the possibility that Thy-1 may play different functions in early and late stages of fibrosis." (PMID 36066980, 2022). "In lung fibrosis, Thy-1/CD90 associates with αvβ5 integrin in cis, promoting the inhibition of latent TGF-β1 activation induced by myofibroblast contraction, likely by competing with the RGD motifs on the N-terminal latency-associated peptide (LAP) and those of ECM proteins." (PMID 31428610, 2019). "In the current study, we further evaluated the critical role of Thy1 protein in lung myofibroblast proliferation and apoptosis in naïve cells and during the evolution of lung fibrosis, as well as its association with profibrotic functions such as differentiation and collagen production." (PMID 30002599, 2018). "Likewise, Thy-1 deficient mice display more severe lung fibrosis in response to an inflammatory injury than wildtype littermates." (PMID 20657842, 2010). "Investigation of the role of Msln, Muc16, and Thy1 in fibrosis and fibroblast activation across multiple organs, demonstrated that Msln−/− mice are protected from cholestatic fibrosis caused by Mdr2 deficiency, bleomycin-induced lung fibrosis, and UUO-induced kidney fibrosis." (PMID 36358290, 2022). "Therefore, although Thy-1 deficiency leads to exacerbated lung fibrosis, in skin it is protective." (PMID 36066980, 2022). "These Thy1‐KO mice displayed persistent myofibroblast and collagen accumulation as well as decreased apoptosis of myofibroblasts, all resulting in a failure of lung fibrosis resolution." (PMID 40936326, 2026). "The low expression of Thy-1 (CD90) is related to its hypermethylation in myofibroblasts of the fibroblastic foci during pulmonary fibrosis." (PMID 38915445, 2024). "This suggested that Thy-1+ (CD90+) fibroblasts can inhibit pulmonary fibrosis and delay the onset of lung disease through the WNT signaling pathway." (PMID 36747131, 2023).